NECTIN1 (nectin cell adhesion molecule 1)
Diseases named in the same sentence as NECTIN1 in open-access papers (continued):
Sharing a sentence is not in itself a finding about the gene and the disease.
tumor (continued). "On average a significantly greater number of pediatric tumor cells expressed more nectin-1 than the adult tumor cells (82.4 ± 15.3% versus 38.8 ± 26.6%; p = 0.0005), suggesting that HSV-1 should be able to enter the pediatric tumor cells more efficiently than the adult tumor cells." (PMID 30224769, 2018). "To compare the in vivo therapeutic effect of Baco-1 and FusOn-H2 against tumors that only express nectin-2 but not HVEM or nectin-1, we implanted A375 tumor cells to the right flank of NOD-SCID mice." (PMID 29765544, 2018). "For example, uterine cervical squamous cell carcinomas expressed nectin-1, but the advancing edge of the tumor nests of this tumor type had absent or reduced nectin-1 expression compared with the center of the tumor nests." (PMID 25690753, 2015). "CD133+ GSCs expressed nectin-1 in similar amounts to CD133- tumor cells in most GBM xenografts tested, including the pediatric GBM xenograft D456MG, which expressed high levels of nectin-1, suggesting that oHSV should be able to enter and infect GSCs and tumor cells equally." (PMID 23450706, 2013). "Levels of Nectin-1 were elevated in estrogen receptor positive (ER+) tumours, when compared to estrogen negative (ER−) (ER+ 609+/−280 versus ER− 152.5+/−29.7)." (PMID 24386110, 2013). "The relative increase in active signal receipt via CD96 may represent compensatory means of tumor immune evasion as cancer cells, CAFs, TAMs, DCs, and mast cells were all found to express PVR and NECTIN1 within our dataset, both of which are capable of inducing immunosuppression in CD8+ T cells." (PMID 39811671, 2025). "Moreover, PVRL1 (CD111, nectin-1) promotes TIGIT-mediated T cell suppression by stabilizing CD155 on the surface of HCC tumor cells, and PVRL1 knockdown in tumor cells in an HCC mouse model resulted in reduced tumor growth in a CD8+ T cell-dependent manner." (PMID 34367161, 2021). "In the absence of NECTIN1, they switch to cell–matrix adhesion and migrate away by activating an integrin/FAK/SRC pathway, leading to tumor dissemination." (PMID 36229674, 2022). "Our data show the following: 1) This subpopulation of tumor cells only express nectin-2, not the other two major receptors (HVEM or nectin-1)." (PMID 29765544, 2018).
cancer (23 papers, 2011 to 2025). A tumor composed of atypical neoplastic, often pleomorphic cells that invade other tissues. "Although limited number of studies have analyzed the role of Nectin1 in tumors, most of these studies have found that Nectin1 expression is associated with cancer progression." (PMID 34625065, 2021). "Abnormal expression of Nectin-1 can be observed in tumors of epithelial origin, such as cervical squamous cell carcinomas, cancer-associated fibroblasts of pancreatic ductal adenocarcinomas, CRCs and gastric cancers, or malignant transformations of keratinocytes." (PMID 36553083, 2022). "High nectin-1 expression in cancer compared to adjacent tissues.Up-regulation of nectin-1 correlated with a worse prognosis and more advanced disease." (PMID 37568798, 2023). "The expression levels of nectin-1 protein in the cancer tissues of 28 patients with HCC were higher than those in paracancerous tissues." (PMID 36059705, 2022). "The expression levels of nectin-1 protein in cancer tissues of 28 patients with HCC (2.55 ± 0.61) were higher than those in paracancerous tissues (1.82 ± 0.94) according to IHC (t = 3.44, p < 0.001)." (PMID 36059705, 2022). "Our laboratory is committed to the construction of cancer-specific oHSVs retargeted to cancer-specific receptors of choice, and detargeted from the natural receptors Nectin1 and HVEM." (PMID 34696515, 2021). "On the study of retargeting oHSVs to EGFR and CEA, which is overexpressed in cancer cells, the AAs 2-24 of gD was deleted and a single AA substitution, Y38C, was introduced to ablate the responsiveness to nectin-1." (PMID 30799657, 2018). "The expression of Nectin 1 on the cell surface of tumors is also a predictor of oncolytic sensitivity to HSV in potential cancer therapy." (PMID 21901103, 2011). "Researchers consistently indicate that the level of nectin-1 expression increases in the cytoplasm of cancer cells, and an increasing number of reports provide data on the correlation between elevated nectin-1 expression and the growing metastatic potential of tumors." (PMID 40244005, 2025). "Further studies are required to investigate the expression of nectin-1 in other cancers and to ascertain whether it exhibits a similar capacity for diagnosis and prognosis." (PMID 40244005, 2025). "Nectin-1 has various patterns of expression in different cancers." (PMID 37568798, 2023). "However, there have been few reports on the roles of nectin-1, nectin-2, and nectin-3 in cancer development and prognosis." (PMID 36059705, 2022). "In such pathological situations, nectin-1 could be a target of choice for NK cells aiming at eliminating cancer cells." (PMID 30759143, 2019). "The results showed that the expression levels of nectin-1 and nectin-2 genes in HCC tissues were higher compared to those in normal tissues adjacent to cancer from all patients (p < 0.001)." (PMID 36059705, 2022). "Therefore, similar to FAM83H, Nectin1 might play different roles in different cancer types." (PMID 34625065, 2021). "Availability of nectin-1 or HVEM correlates directly with HSV-1 infection efficiency in cell lines, cancer cells and tissues." (PMID 31581238, 2019). "This is in contrast to the results from our previous studies on tumors formed from other cancer cell lines that express HEVM and/or nectin-1, which showed that Baco-1 produced clearly measurable antitumor activities on all these tumors." (PMID 29765544, 2018). "As previously stated, Nectin-4 has been shown to interact in trans with Nectin-1/PVRL1 on adjacent cells, which triggers proliferation of the cancer cell through interaction in cis with V β6 integrin." (PMID 27657109, 2016). "Oncolytic HSV infection of cancer cells relies on increased expression of multiple receptors in cancer cells such as herpesvirus entry mediator (HVEM), a member of the TNF superfamily, and nectin-1." (PMID 34771615, 2021).
cancer (continued). "According to the reports, some cancer cells are resistant to oHSVs because of a lack of the natural receptor nectin-1." (PMID 30799657, 2018).
adenocarcinoma (1 paper, 2015). A common cancer characterized by the presence of malignant glandular cells. "In the adenocarcinoma cells, nectin-1 and -3 demonstrated both membranous and cytoplasmic expression." (PMID 25690753, 2015).
CNS tumor (1 paper, 2021). "For brain and CNS tumor samples, CADM1, CADM2, NECTIN1, and NECTIN3 were downregulated, whereas NECTIN2 was overexpressed." (PMID 34925438, 2021).
immune dysfunction (1 paper, 2025). "Among the four genes that were consistently upregulated in ARHL patients (FASLG, NCAM1, MARCO, and NECTIN1), FASLG was prioritized for further validation based on its strong association with immune-mediated apoptosis and its previously reported role in age-related immune dysfunction." (PMID 40971385, 2025).
infectious disease (1 paper, 2018). A disorder directly resulting from the presence and activity of a microbial, viral, or parasitic agent in humans. "For preventive medicine of infectious diseases, the soluble forms of nectin-1, HVEM and Siglec-9 that directly bind to pathogens may be useful agents, but so far there is no apparent evidence of their potential for treatment of infectious disease." (PMID 29342882, 2018).
neurological disorders (1 paper, 2022). "Meanwhile, nectin-1 mediates synaptogenesis in neurological disorders." (PMID 35625034, 2022).
NECTIN1 also shares sentences with these, for which no sentence is quoted: cleft lip (5 papers); autosomal recessive ectodermal dysplasia (2); cervical cancer (2); cleft lip and palate (2); orofacial cleft (2); psychiatric disorder (2); syndactyly (2); thyroid cancer (2); basal cell carcinoma (1); bladder pain syndrome (1); bone cancer (1); bone metastasis (1); Bowen’s disease (1); chronic rhinosinusitis (1); cognitive disorder (1); COVID-19 (1); cystic fibrosis (1); embryonal tumor (1); gastrointestinal tract infection (1); HCMV infection (1); head/neck carcinoma (1); Herpes Simplex (1); Hypertension (1); keratitis (1); Krabbe disease (1); leprosy (1); lip (1); lung carcinoma (1); malignant peripheral nerve sheath tumor (1); malignant rhabdoid kidney tumor (1).
A further 9 diseases each share a sentence with NECTIN1 in 1 paper.